RAB10 (RAB10, member RAS oncogene family)
Description:
The small GTPases Rab are key regulators of intracellular membrane trafficking, from the formation of transport vesicles to their fusion with membranes. Rabs cycle between an inactive GDP-bound form and an active GTP-bound form that is able to recruit to membranes different set of downstream effectors directly responsible for vesicle formation, movement, tethering and fusion. RAB10 is mainly involved in the biosynthetic transport of proteins from the Golgi to the plasma membrane. Regulates, for instance, SLC2A4/GLUT4 glucose transporter-enriched vesicles delivery to the plasma membrane (By similarity). In parallel, RAB10 regulates the transport of TLR4, a toll-like receptor to the plasma membrane and therefore may be important for innate immune response (By similarity). Also plays a specific role in asymmetric protein transport to the plasma membrane. In neurons, involved in axonogenesis through regulation of vesicular membrane trafficking toward the axonal plasma membrane (By similarity). In epithelial cells, regulates transport from the Golgi to the basolateral membrane. May play a role in the basolateral recycling pathway and in phagosome maturation (By similarity). May play a role in endoplasmic reticulum dynamics and morphology controlling tubulation along microtubules and tubules fusion. Together with LRRK2, RAB8A, and RILPL1, regulates ciliogenesis. When phosphorylated by LRRK2 on Thr-73, binds RILPL1 and inhibits ciliogenesis. Participates in the export of a subset of neosynthesized proteins through a Rab8-Rab10-Rab11-dependent endososomal export route. Targeted to and stabilized on stressed lysosomes through LRRK2 phosphorylation where it promotes the extracellular release of lysosomal content through EHBP1 and EHNP1L1 effector proteins. (Microbial infection) Upon Legionella pneumophila infection promotes endoplasmic reticulum recruitment and bacterial replication. Plays a role in remodeling the Legionella-containing vacuole (LCV) into an endoplasmic reticulum-like vacuole.
Tractability: Small molecule: a structure with a bound ligand is known. Antibody: UniProt places it where antibodies can reach, with high confidence; its Gene Ontology location is reachable by antibodies, with high confidence. PROTAC: UniProt records ubiquitination sites on it; ubiquitination databases record sites on it; its protein half-life has been measured; a small molecule that binds it is known.
Target class: Enzyme; Hydrolase
Gene: Protein-coding gene on chromosome 2 (26,033,481 to 26,138,436, forward strand). Ensembl gene ENSG00000084733.
Subcellular location: Cytoplasmic vesicle membrane; Golgi apparatus membrane; Golgi apparatus, trans-Golgi network membrane; Endosome membrane; Recycling endosome membrane; Cytoplasmic vesicle, phagosome membrane; Cytoplasm, cytoskeleton, cilium basal body; Endoplasmic reticulum membrane; Cytoplasm, perinuclear region; Lysosome
Pathways (Reactome):
Vesicle-mediated transport: RAB GEFs exchange GTP for GDP on RABs; Translocation of SLC2A4 (GLUT4) to the plasma membrane
Immune System: Neutrophil degranulation
Metabolism of proteins: RAB geranylgeranylation
Gene Ontology:
Molecular function: cadherin binding involved in cell-cell adhesion; GDP binding; GTP binding; GTPase activity; myosin V binding; protein binding; G protein activity
Biological process: antigen processing and presentation; endoplasmic reticulum tubular network organization; endosomal transport; establishment of protein localization to endoplasmic reticulum membrane; establishment of protein localization to membrane; negative regulation of motile cilium assembly; regulated exocytosis; axonogenesis; cellular response to insulin stimulus; establishment of neuroblast polarity; exocytosis; Golgi to plasma membrane protein transport; Golgi to plasma membrane transport; polarized epithelial cell differentiation; protein localization to basolateral plasma membrane; protein localization to plasma membrane; vesicle-mediated transport; cell-cell adhesion; endocytic recycling
Cellular component: adherens junction; cilium; endoplasmic reticulum membrane; endoplasmic reticulum tubular network; endosome; endosome membrane; exocytic vesicle; extracellular exosome; focal adhesion; Golgi apparatus; Golgi membrane; insulin-responsive compartment; plasma membrane; recycling endosome; cytoplasmic vesicle membrane; cytosol; exocyst; perinuclear region of cytoplasm; recycling endosome membrane; secretory granule membrane; secretory vesicle; trans-Golgi network; lysosome; phagocytic vesicle membrane
Genetic constraint (gnomAD): Loss-of-function variants: 3 observed, 14.85 expected, observed/expected ratio (o/e) 0.2, 90% interval 0.091 to 0.52. The upper end of that interval is the gene's LOEUF score, 0.52, which puts it in group 2 of 6, group 1 being the genes least tolerant of losing a copy. Missense variants: 89 observed, 213.49 expected, observed/expected ratio (o/e) 0.42, 90% interval 0.35 to 0.5. Synonymous variants: 83 observed, 81.27 expected, observed/expected ratio (o/e) 1.02, 90% interval 0.85 to 1.23.
Homologues: Orthologues: chimpanzee RAB10 (100% identical), macaque RAB10 (100% identical), mouse Rab10 (100% identical), rat Rab10 (100% identical), dog RAB10 (99% identical), zebrafish rab10 (96% identical), rabbit RAB10 (95% identical), pig RAB10 (88% identical), tropical clawed frog rab10 (88% identical), guinea pig RAB10 (85% identical). Paralogues in human: RAB8A (70% identical), RAB8B (70% identical), RAB13 (62% identical), RAB1A (54% identical), RAB1B (54% identical), RAB12 (50% identical), RAB26 (50% identical), RAB3B (50% identical), RAB37 (49% identical), RAB3C (49% identical), RAB35 (48% identical), RAB3A (48% identical), and 56 more.
Diseases named in the same sentence as RAB10 in open-access papers:
RAB10 is named in the same sentence as 67 diseases in open-access papers, as found by Europe PMC text mining. Sharing a sentence is not in itself a finding about the gene and the disease. The quoted sentences say what the papers report.
Parkinson disease (20 papers, 2017 to 2025). A progressive degenerative disorder of the central nervous system characterized by loss of dopamine producing neurons in the substantia nigra and the presence of Lewy bodies in the substantia nigra and locus coeruleus. "The most common cause of familial Parkinson’s disease is linked to mutations in the leucine rich-repeat kinase 2 (LRRK2) protein that phosphorylates Rab10, Rab8a, Rab12 and Rab35." (PMID 40801573, 2025). "In future work, it would be very interesting to use the MJFF-pRAB10 phospho-specific antibody to investigate Rab10 phosphorylation levels in brain samples derived from LRRK2-mutated Parkinson's disease patients." (PMID 29127256, 2018). "Given that several LRKK2 variants increase LRKK2 kinase activity toward Rab10, an emerging new approach for disease modification in Parkinson’s disease is inhibition of the LRRK2-Rab signaling pathway and subsequently restoring normal membrane trafficking and lysosomal activity." (PMID 37156612, 2023). "Furthermore, LRRK2-mediated Rab10 phosphorylation is increased in neutrophils as well as monocytes isolated from three Parkinson's patients with a heterozygous VPS35[D620N] mutation compared with healthy donors and idiopathic Parkinson's patients." (PMID 29743203, 2018). "We speculate that G2019S LRRK2 mutation carriers would have the highest levels of Rab10 phosphorylation followed by those with sporadic Parkinson's, while healthy controls would have the lowest levels." (PMID 29127255, 2018). "Further, compared to LRRK2 WT the disease variants G2019S and R1441C exhibits increased pThr73 levels in HEK293 cells thereby confirming literature reports that LRRK2 exonic variation associated with Parkinson’s disease impacts the level of Rab10 phosphorylation." (PMID 28860483, 2017). "This relationship underscores the importance of Rab10 in cellular processes related to disease pathology, specifically Parkinson’s disease." (PMID 40535172, 2024). "To better understand the ratio of pT73-Rab10 to total Rab10 in the periphery in iPD, we selected a cohort of serum samples donated from participants enrolled in the Parkinson’s Disease Biomarker Program (PDBP)." (PMID 38862989, 2024). "Despite increasing evidence that Rab10 serves as a neuroprotective factor for Alzheimer’s and Parkinson’s disease, the mechanism behind the apparent protection remains mysterious." (PMID 37156612, 2023). "Considering that the genetic variation in LRRK2 enhances susceptibility to the second most common neurodegenerative disorder, Parkinson’s disease, these findings render Rab10 signaling pathways as the common mechanisms of neurodegeneration." (PMID 37156612, 2023). "Rab10 and its phosphorylated form, pRab10 likely play a role in neurodegenerative diseases including Parkinson’s and Alzheimer’s diseases." (PMID 38110990, 2023). "The Parkinson's-disease-associated LRRK2 kinase phosphorylates multiple Rab GTPases including Rab8 and Rab10, which enhances their binding to RILPL1 and RILPL2." (PMID 35776681, 2022). "For instance, RAB10 binds to the autophagy receptor optineurin to promote mitochondrial autophagy in Parkinson’s disease." (PMID 35030981, 2022). "We exploit this assay to demonstrate that in Parkinson's patients with VPS35[D620N] mutations, phosphorylation of multiple Rab proteins (Rab1, Rab3, Rab8, Rab10 and Rab43) is elevated." (PMID 33367571, 2021). "Here we describe an accurate and highly-sensitive MS-assay for determining the Rab10-Thr73 phosphorylation stoichiometry and how it changes in Parkinson's disease." (PMID 32601174, 2020). "Parkinson’s disease-associated LRRK2 kinase phosphorylates multiple Rab GTPases, including Rab8A and Rab10." (PMID 30398148, 2018). "Using this approach, only the same sample from the 91-year-old female Parkinson's patient displayed significant levels of phosphorylated Rab10." (PMID 29127256, 2018).
Parkinson disease (continued). "By including participants with LRRK2 G2019S associated Parkinson's, we anticipated to gain more insights into the effect size of LRRK2 kinase activity by means of Rab10 phosphorylation." (PMID 29127255, 2018). "We also provide the first evidence that the phospho-specific Rab10 antibody can be employed to detect elevated phosphorylation of Rab10 in the human brain sample derived from Parkinson's disease patients." (PMID 29127256, 2018). "However, the knockdown of Rab10 in dopaminergic neurons is reported to completely reverse the Parkinson’s related bradykinesia caused by LRRK2-G2019S, indicating that the knockdown of Rab10 can promote behavioral activity." (PMID 39669198, 2024). "The high abundance of Rab10 in neutrophils and the promise of pThr73 as a biomarker for Parkinson's disease encouraged us to develop a highly accurate and sensitive targeted MS-based assay for quantifying phosphorylated Rab10 in human cells at the peptide level." (PMID 32601174, 2020). "It would also be interesting to investigate whether Parkinson's patients with PARK16 mutations display elevated LRRK2 kinase activity and Rab10 phosphorylation." (PMID 29212815, 2018). "However, phosphorylated Rab10 was elevated in a few samples, especially in one of the idiopathic Parkinson's samples (donor 1, derived from a 91-year-old female patient with no known mutations)." (PMID 29127256, 2018). "Furthermore, we elaborate methods to quantitatively assess LRRK2-mediated Rab10 phosphorylation in human neutrophils including the study of a few clinical samples from LRRK2 G2019S associated and sporadic Parkinson's patients as well as controls." (PMID 29127255, 2018). "In mouse melanocytes, which express high levels of Rab38, Rab32, and Rab29, knockdown (or CRISPR knockout) of Rab38, but not Rab32 or Rab29, decreases phosphorylation of multiple LRRK2 substrates, including Rab10 and Rab12, by both endogenous LRRK2 and exogenous Parkinson’s disease-mutant LRRK2." (PMID 37625589, 2023). "The purpose of the present study was to test the practicability of assessing LRRK2-mediated Rab10 phosphorylation in a patient cohort in a clinical setting and not to address whether Rab10 phosphorylation is elevated in patients with Parkinson's or G2019S carriers." (PMID 29127255, 2018).
hepatocellular carcinoma (11 papers, 2017 to 2025). A malignant tumor that arises from hepatocytes. "Consistent with our findings in EC, elevated LMO3 expression has been associated with poor prognosis in gastric cancer and neuroblastoma, PRKAA2 in endometrial cancer and RAB10 in breast cancer and hepatocellular carcinoma." (PMID 40804485, 2025). "It is reported that knockdown of RAB10 arrests the growth cycle and colony formation, as well as promotes cell apoptosis in hepatocellular carcinoma cells; in addition, high RAB10 expression correlates with poor prognosis of the patients." (PMID 36371494, 2022). "RAB10 is a member of the Ras-related protein family and has been reported to function as an oncogenic gene in cervical cancer, hepatocellular carcinoma, esophageal squamous cell carcinoma, and osteosarcoma." (PMID 35030981, 2022). "Rab10 silencing inhibits the HGF pathway, while Rab10 overexpression indicates poor prognosis of hepatocellular carcinoma." (PMID 34141705, 2021). "Previous studies have demonstrated that RAB10 is an oncogenic gene in esophageal squamous cell carcinoma, osteosarcoma and hepatocellular carcinoma." (PMID 32774162, 2020). "We recently identified RAB10, encoding a small GTPase, as a positive regulator of LDL uptake in hepatocellular carcinoma cells (HuH7) in a genome-wide CRISPR screen, though the underlying molecular mechanism for this effect was unknown." (PMID 35753407, 2022). "In this respect, it is of interest that RAB10 dysregulation was reported in some cases of hepatocellular carcinoma, which may support its key role in protein trafficking in hepatocytes." (PMID 34209301, 2021). "Rab10 could induce the recruitment of autophagosomes at the LD surface in hepatocellular carcinoma." (PMID 34141705, 2021).
osteosarcoma (9 papers, 2017 to 2024). A usually aggressive malignant bone-forming mesenchymal neoplasm, predominantly affecting adolescents and young adults. "The present study provided evidence that Rab10 was overexpressed in osteosarcoma, and that its positive expression is associated with distant metastasis and a higher TNM stage." (PMID 33479458, 2021). "RAB10 expression is increased in various malignancies such as stomach cancer, cervical cancer, osteosarcoma, glioma, and HCC." (PMID 38364252, 2024). "Some studies have demonstrated that EBLN3P promotes the progression of liver cancer via alteration of microRNA-144-3p/DOCK4 pathway, and osteosarcoma through modifying the miR-224-5p/Rab10 signaling axis." (PMID 35517503, 2022). "Accordingly, these data suggested that the regulatory effects of EBLN3P were mediated through the miR-224-5p/Rab10 axis to promote the progression of osteosarcoma cells." (PMID 33479458, 2021). "The results of western blot analysis demonstrated that the protein expression level of Rab10 were expressed at higher levels in four osteosarcoma cell lines compared with those in the normal human fetal osteoblast cell line (normalized to β-actin expression)." (PMID 33479458, 2021). "Osteosarcoma patients with positive Rab10 expression exhibited a shorter overall survival compared with patients with negative Rab10 expression." (PMID 33479458, 2021). "The effects of Rab10 on osteosarcoma cells and its interaction with miR-224-5p have yet to be elucidated." (PMID 33479458, 2021). "Further rescue experiments demonstrated that EBLN3P promoted the proliferation and metastasis of osteosarcoma cells via regulation of the miR-224-5p/Rab10 signaling axis." (PMID 33479458, 2021). "The increased expression of EBLN3P and Rab10 and decreased expression of miR-224-5p were observed in osteosarcoma tissues and cell lines." (PMID 33479458, 2021). "A recent study investigated the expression of Rab10 in osteosarcoma cells and its involvement in the regulation of cell proliferation and migration." (PMID 33479458, 2021). "The present study demonstrated that Rab10 could promote the proliferation of osteosarcoma cells in vitro." (PMID 33479458, 2021). "Furthermore, EBLN3P act as a ceRNA to regulate Rab10 expression via competitively sponging to miR-224-5p, thereby regulating the progression of osteosarcoma." (PMID 33479458, 2021). "Further RT-qPCR and western blot analysis validated that the overexpression of miR-224-5p significantly reduced the expression of Rab10, whereas knockdown of miR-224-5p significantly enhanced the expression of Rab10 at both the mRNA and protein levels in 143B osteosarcoma cells." (PMID 33479458, 2021). "At present, the expressions of EBLN3P and miR-224-5p in osteosarcoma tissues were quantified by reverse transcription-quantitative PCR assay, and the expression of Ras-related protein 10 (Rab10) in osteosarcoma tissues was quantified by immunohistochemistry and western-blotting." (PMID 33479458, 2021). "The aim was to determine whether EBLN3P can affect the malignant phenotype of osteosarcoma cells by regulating Rab10 protein expression." (PMID 33479458, 2021). "In addition, osteosarcoma patients with positive EBLN3P or Rab10 expression had a shorter overall survival compared with that of patients with negative EBLN3P or Rab10 expression." (PMID 33479458, 2021). "According to the results of previous and ongoing research, it was hypothesized that EBLN3P can affect the malignant phenotype of osteosarcoma cells by upregulating the expression of the Rab10 protein." (PMID 33479458, 2021). "It was also observed that the expression of Rab10 in distant metastases was higher compared with that in primary osteosarcoma tissues, and that Rab10 could increase the migration and invasion abilities of osteosarcoma cells in vitro and in vivo." (PMID 33479458, 2021). "In addition, EBLN3P could regulate the expression of Rab10 through competitive sponging action with miR-224-5p in osteosarcoma." (PMID 35473552, 2022).
osteosarcoma (continued). "Furthermore, the expression of Rab10 in osteosarcoma tissues was investigated via IHC analysis." (PMID 33479458, 2021). "Subsequently, we found that Lentivirus-mediated RAB10 knockdown markedly inhibited HCC cell proliferation in vitro, which was consistent with other study in osteosarcoma." (PMID 28460436, 2017). "In the present study, it was also observed that the expression of Rab10 was regulated via the EBLN3P/miR-224-5p axis through bioinformatics analyses; however, whether this compensatory mechanism exists in osteosarcoma requires further investigation." (PMID 33479458, 2021). "The expression of Rab10 was higher in osteosarcoma tissues (21/29) compared with that in non-neoplastic bone tissues (5/27), and the expression of Rab10 was found to be associated with pulmonary metastasis (P < 0.001) and TNM stage (AJCC) (P < 0.001)." (PMID 33479458, 2021). "Besides, the protein expression of Rab10 was higher in osteosarcoma tissues compared with non-neoplastic bone tissues (normalized to β-actin expression)." (PMID 33479458, 2021). "Furthermore, the mechanistic investigations revealed activation of the miR-224-5p/Rab10 regulatory loop by knockdown of miR‐372-3p or overexpression of Rab10, thereby confirming the in vitro role of EBLN3P in promoting osteosarcoma cell proliferation, migration and invasion." (PMID 33479458, 2021). "In addition, the expression levels of EBLN3P, miR-224-5p and Rab10 were accessed in osteosarcoma tissues and non-neoplastic bone tissues." (PMID 33479458, 2021).